GBP5 (guanylate binding protein 5)
Diseases named in the same sentence as GBP5 in open-access papers (continued):
Sharing a sentence is not in itself a finding about the gene and the disease.
Hepatitis (3 papers, 2022 to 2025). Inflammation of the liver. "GBP5 has shown higher specificity in detecting liver injury related to EBV induced hepatitis in children, it is considered to be the cause of liver injury in children with IM." (PMID 40075517, 2025). "In addition, most of these genes have a risk coefficient greater than 0 (AC008271.1, C11orf53, F2RL2, GBP5, LUCAT1, RP11‐149I23.3, RP11‐383 J24.1 and SLC35G2), except for CASP8 and RP11‐114B7.6, suggesting that these genes are adverse prognostic factors in hepatitis‐positive HCC patients." (PMID 35637633, 2022).
lung carcinoma (3 papers, 2024 to 2025). "GBP5 increases lung cancer infiltration of B cells, CD4+ and CD8+ T cells, and NK cells, potentially sensitizing tumors to PD-L1 blockade or other immunotherapies, mediated by its Golgi localization and interferon-driven immune checkpoint modulation." (PMID 40564939, 2025). "In lung cancer, photodynamic therapy, namely a novel approach that integrates the photodynamic effect with anti-tumor immunotherapy, induces GBP5 expression in macrophages, promoting their polarization toward anti-tumor activity." (PMID 40788157, 2025).
pulmonary TB (3 papers, 2022 to 2026). "Some studies report elevated GBP5 levels with strong diagnostic potential, while others identify downregulation in pulmonary tuberculosis patients." (PMID 40788157, 2025).
rheumatoid arthritis (3 papers, 2024 to 2025). A chronic, systemic autoimmune disorder characterized by inflammation in the synovial membranes and articular surfaces. "Other compounds, such as Aescin and Sinomenine (SIN), modulate GBP5 to mitigate symptoms in chemotherapy-induced phlebitis and rheumatoid arthritis, respectively." (PMID 40788157, 2025). "In disorders such as rheumatoid arthritis (RA), osteoarthritis (OA), phlebitis, and IBD, GBP5 activates the NLRP3 inflammasome, thereby increasing IL-1β and IL-18 production, which exacerbates local inflammation (55, 138, –, 140)." (PMID 40788157, 2025).
rosacea (3 papers, 2023 to 2025). A chronic erythematous skin disorder that affects the face. "For instance, guanylate-binding protein 5 (GBP5) promotes M1 macrophage polarization via the NF-κB signaling pathway, amplifying skin inflammation in rosacea." (PMID 40474977, 2025). "Previous studies showed that GBP5 and ADAMDEC1 played a pro-inflammatory role in rosacea-like skin inflammation by regulating the M1 macrophage polarization." (PMID 38250077, 2023).
asthma (2 papers, 2021 to 2022). "To date, no studies have reported on the relationship between CD3D, CD3G, RGS1, HLA-DMB, GBP4, GBP5, and asthma." (PMID 36118895, 2022). "On the other hand, two genes are not involved in regulating protein complex assembly; those are GBP5, which has a role in the innate immune system and inflammation, and PHF11, which is linked to asthma." (PMID 35003208, 2021).
dilated cardiomyopathy (2 papers, 2022 to 2025). Cardiomyopathy which is characterized by dilation and contractile dysfunction of the left and right ventricles. "GBP5 and GBP6 were increased in cardiomyocytes of ICI-associated myocarditis (ICIM) patients compared to patients with dilated cardiomyopathy and virus-induced myocarditis." (PMID 35222540, 2022). "In particular, GBP5 and GBP6 were elevated in these samples compared to viral myocarditis, and absent in biopsies from patients with dilated cardiomyopathy." (PMID 40940808, 2025).
E. coli infections (2 papers, 2017 to 2022). "Based on these previous findings, we asked whether GBP5 modulated inflammasome activation in response to E. coli infections or OMV treatment in macrophages." (PMID 28974614, 2017).
lymph node metastasis (2 papers, 2020 to 2021). "Our clinical data indicated that high gene expression levels of GBP5 are associated with shorter DFS in oral cancer patients with lymph node metastasis." (PMID 34439200, 2021). "This study found that the high expression levels of GBP5 are associated with cancer malignancy and poor prognosis in oral cancer patients with poor cell differentiation and lymph node metastasis, indicating that GBP5 might play an oncogenic role in OSCC." (PMID 34439200, 2021).
lymphoma (2 papers, 2021). A malignant (clonal) proliferation of B- lymphocytes or T- lymphocytes which involves the lymph nodes, bone marrow and/or extranodal sites. "Regarding current studies of GBP5 in cancers, a truncated splice variant of GBP5 was found in lymphoma." (PMID 34439200, 2021).
measles (2 papers, 2021 to 2022). A highly contagious viral infection caused by the measles virus. "Knockdown of GBP2 and GBP5 led to increased production of HIV-1, and complete depletion of GBP5 also facilitated the replication of influenza A, measles, and Zika viruses." (PMID 33673837, 2021). "Ectopic expression of GBP2 and GBP5 suppressed various viruses' replication, including human immunodeficiency virus-1 (HIV-1), influenza A, murine leukemia, Zika, measles, and Marburg viruses." (PMID 33673837, 2021).
myocarditis (2 papers, 2022 to 2025). Myocarditis is a condition that is characterized by inflammation of the heart muscle (myocardium). "Consistent with observations in endomyocardial biopsies from patients with ICI-induced myocarditis, we observed increased GBP5 protein expression and CASP-1 cleavage following cytokine treatment." (PMID 40940808, 2025).
neuroblastoma (2 papers, 2022 to 2024). Neuroblastoma (NB) is the most common solid, extracranial childhood tumor. "We further validated our results in JEV infected human neuroblastoma SH-SY5Y cells, where we observed significantly enhanced transcript levels of Gbp1, Gbp2, Gbp4 & Gbp5." (PMID 35663470, 2022).
oral cancer (2 papers, 2021 to 2025). "Our results indicated that oral cancer patients with high expression levels of GBP5 have poor DFS, which is usually caused by chemotherapy resistance-associated cancer stemness." (PMID 34439200, 2021). "Moreover, high gene expression levels of GBP5 were associated with poor prognosis in oral cancer patients having poor cell differentiation and lymph node metastasis." (PMID 34439200, 2021). "GBP5 functions as a biomarker predicting a good response to immune checkpoint inhibitor therapy in oral cancer." (PMID 40909948, 2025). "TCGA data analysis indicated that the gene expression levels of GBP5 in 303 tumor tissues of oral cancer patients were higher than those in 29 normal tissues (p < 0.001)." (PMID 34439200, 2021). "The gene expression of markers for epithelial−mesenchymal transition and cancer stemness was also reduced in GBP5-silenced oral cancer cells." (PMID 34439200, 2021). "Next, we investigated the prognostic role of GBP5 in oral cancer patients from the TCGA database." (PMID 34439200, 2021). "Furthermore, co-expressions of GBP5/CD166 (AHR = 2.48, CI = 1.08–5.74, p = 0.033) and GBP5/ ABCG2 (AHR = 2.65, CI = 1.25–5.61, p = 0.011) genes are associated with DFS in oral cancer patients from TCGA database." (PMID 34439200, 2021). "Moreover, the gene expression levels of GBP5 in tumor tissues were higher compared with CTAN tissues in 30 oral cancer patients from the TCGA database (p < 0.001)." (PMID 34439200, 2021). "Gene expression levels of GBP5 were higher in tumor tissues in our OSCC patients and in oral cancer patients from The Cancer Genome Atlas (TCGA) database." (PMID 34439200, 2021). "Higher gene expression levels of GBP5 were also found in tumor tissues of 23 buccal mucosal squamous cell carcinoma (BMSCC)/14 tongue squamous cell carcinoma (TSCC) patients and 30 oral cancer patients from The Cancer Genome Atlas (TCGA) database compared with those in CTAN tissues." (PMID 34439200, 2021).
osteoarthritis (2 papers, 2025). A noninflammatory degenerative joint disease occurring chiefly in older persons, characterized by degeneration of the articular cartilage, hypertrophy of bone at the margins and changes in the synovial membrane. "In osteoarthritis, GBP5 expression is significantly upregulated in TNF‐α‐treated chondrocytes, where IRF1 promotes GBP5 transcription, triggering NLRP3 inflammasome activation and promoting pyroptosis." (PMID 40636987, 2025). "In inflammatory conditions, GBP5 promotes chondrocyte pyroptosis by upregulating pyroptosis-related genes, such as NLRP3, Caspase-1, and Gasdermin D (GSDMD), through the NLRP3 inflammasome pathway, contributing to osteoarthritis progression." (PMID 40788157, 2025).
parasitic infection (2 papers, 2021 to 2025). "GBP5 is markedly upregulated during infections, demonstrating diverse immunoregulatory functions in bacterial, viral, and parasitic infections." (PMID 40788157, 2025). "In parasitic infections, GBP5 exerts direct antiparasitic effects while enhancing host immunity." (PMID 40788157, 2025).
psoriasis (2 papers, 2024 to 2025). An autoimmune condition characterized by red, well-delineated plaques with silvery scales that are usually on the extensor surfaces and scalp. "We identified GZMB, GNAS, GBP5, FOXP3, LSP1 and CD81 as characteristic genes of psoriasis-associated CD8+ T cells, among which, Granzyme B (GzmB), a serine protease, is produced by natural killer (NK) cells and CD8+ T cells, and is an vital mediator of skin injury, inflammation and repair." (PMID 38915827, 2024). "We speculate that GBP5 may be involved in the pathogenesis of psoriasis by regulating inflammatory signaling pathways, such as IFN-γ signaling pathway." (PMID 38915827, 2024). "Our results suggest that the high expression of GZBM, GBP5 and FOXP3 in CD8+ T cells drives the pathogenesis of psoriasis, therefore, inhibiting the expression of GZBM, GBP5 and FOXP3 is expected to be a new strategy to alleviate the progression of psoriasis." (PMID 38915827, 2024).
sarcoidosis (2 papers, 2020 to 2022). Sarcoidosis is a multisystemic disorder of unknown cause characterized by the formation of immune granulomas in involved organs. "Top up-regulated genes in sarcoidosis include interferon signature genes such as GBP5 and IFITM1, indicating active regulation of the interferon signaling." (PMID 36203777, 2022).
T cell lymphomas (2 papers, 2016 to 2019). "In this regard, it is worth noting that, GBP5ta, a splicing variant of GBP5 that is associated with the T-cell lymphoma tissues, naturally lacks the GED domain." (PMID 31216343, 2019).
acute myeloid leukemia (1 paper, 2024). Acute myeloid leukemia (AML) is a group of neoplasms arising from precursor cells committed to the myeloid cell-line differentiation. "From the result of pan-cancer analysis, we found that GBP5 positively correlated with M1-type macrophage score in most types of cancer, except acute myeloid leukemia (LAML) when evaluated by CIBERSORT, while the results of total macrophage score and M2-type macrophage scores were less correlated." (PMID 38817865, 2024).
atherosclerosis (1 paper, 2014). A disease characterized by the build-up of fatty material and calcium deposition in the arterial wall resulting in partial or complete occlusion of the arterial lumen. "This is not the case for GBP5, Ubd, SectM1, Ifi16, Upp1 and Fam26F, and could therefore represent potential novel biomarkers of atherosclerosis." (PMID 25478796, 2014).
celiac disease (1 paper, 2023). An autoimmune genetic disorder with an unknown pattern of inheritance that primarily affects the digestive tract. "Similar to celiac disease, expression levels of GBP5, CXCL10, IFI27, and IFNG were increased in tissues of patients with no or low-grade intestinal injury." (PMID 36282455, 2023).
cervical cancer (1 paper, 2025). A primary or metastatic malignant neoplasm involving the cervix. "The analysis showed that OAS2, KLHDC7B, STAT1, TYMP, PSME2 and GBP5 were significantly upregulated in cervical cancer cells compared with normal epithelial cells." (PMID 40259929, 2025).
Chronic colitis (1 paper, 2024). A chronic inflammatory disease of the large intestine (colon, cecum and rectum). "In this work, we show that Gbp5 deficiency protects mice from dextran sulfate sodium (DSS)-induced chronic colitis." (PMID 39062588, 2024). "This study demonstrates that Gbp5 deficiency reduces susceptibility to DSS-induced chronic colitis." (PMID 39062588, 2024). "We found that Gbp5 deficiency protected mice from DSS-induced chronic colitis." (PMID 39062588, 2024). "Here, we explored the functional significance of GBP5 using Gbp5 knockout mice and wildtype mice exposed to dextran sulfate sodium (DSS) to generate chronic colitis model." (PMID 39062588, 2024).
cocaine use disorder (1 paper, 2025). A substance-related disorder that involves the recurring use of cocaine despite negative consequences. "For instance, in cocaine use disorder (CUD), reduced GBP5 levels correlate with severe anhedonia, suggesting that GBP5 may contribute to this condition via immune and inflammatory dysregulation." (PMID 40788157, 2025).
colorectal tumor (1 paper, 2022). "At the protein level, GBP5 expression was also higher in colorectal tumor tissues than in normal tissues (p = 5.20438594686653e-07)." (PMID 36246628, 2022).
Crohn disease (1 paper, 2023). A gastrointestinal disorder characterized by chronic inflammation involving all layers of the intestinal wall, noncaseating granulomas affecting the intestinal wall and regional lymph nodes, and transmural fibrosis. "Compatible with this interpretation was the high expression of GBP5 and IRF1 in VA, which was not further induced by NV, since GBP5 is induced in the M1 subset upon LPS/IFN-γ stimulation, upon HIV infection and in active Crohn’s disease and ulcerative colitis (UC) patients." (PMID 36282455, 2023).
endometriosis (1 paper, 2024). The growth of functional endometrial tissue in anatomic sites outside the uterine body. "HOOK1 is strongly associated with M2 macrophages in endometriosis, and GBP5 is associated with a high infiltration of B-cells, CD4+ T-cells, CD8+ T-cells, and NK-cells in small cell lung cancer." (PMID 38384272, 2024).
endotoxemia (1 paper, 2018). "Interestingly, we found that GBP2 deficiency fails to significantly inhibit caspase-11-dependent immune responses in endotoxemia; whereas genetic deletion of GBP1, GBP2, GBP3, GBP5 and GBP7 simultaneously blocked endotoxemia-induced caspase-11 activation." (PMID 30587103, 2018).
extrapulmonary tuberculosis (1 paper, 2022). A tuberculosis that occurs at body sites other than the lung. "The reactivity of the GBP5 assay between pulmonary and extrapulmonary tuberculosis patients was comparable (p = 0.661)." (PMID 35369870, 2022).
inflammatory skin disease (1 paper, 2024). Inflammatory skin disorders covers a broad category that includes many conditions ranging in severity, from mild itching to grave medical health complications These disorders are common in people of all ages and races. "Guanylate binding protein 5 (GBP5), a member of the guanosine triphosphatase family, is involved in immune and inflammatory responses, and its expression is induced by type I and type II interferons, suggesting a potential role for the GBP5 in inflammatory skin diseases." (PMID 38915827, 2024).
insulinoma (1 paper, 2025). "LPS also does not activate NF-κB in C57BL/6 islets as assessed by IκBα degradation 30 min after LPS stimulation, nor does it stimulate Nos2, Gbp2, or Gbp5 expression by rat insulinoma INS832/13 cells." (PMID 41093076, 2025).
leprosy (1 paper, 2019). Leprosy is a chronic infectious disease affecting primarily the skin and peripheral nervous system. "GBP1, GBP2 and GBP5 are specific to the RR signature in comparison to the other clinical forms of leprosy." (PMID 31600201, 2019).
lip squamous cell carcinoma (1 paper, 2021). "Immunohistochemical results showed that protein expression levels of GBP5 were also higher in the tumor tissues of 353 OSCC patients including 117 BMSCC, 187 TSCC, and 49 lip squamous cell carcinoma patients." (PMID 34439200, 2021).
lupus (1 paper, 2025). "For example, GBP5, which encodes an interferon-inducible GTPase involved in inflammatory responses and lupus nephritis progression in mice exhibited both mutually exclusive exon usage and exon skipping in lupus neutrophils compared to healthy controls." (PMID 41279038, 2025). "GBP5+ neutrophils with elevated interferon signatures have also been identified in inflamed human tissues, such as nasal polyps, indicating broader relevance beyond lupus." (PMID 41279038, 2025).
malignant glioma (1 paper, 2021). A grade III or grade IV glioma arising from the central nervous system. "In this study, we investigated the biological role of GBP5 in malignant gliomas." (PMID 33608513, 2021).
myocardial infarction (1 paper, 2025). Gross necrosis of the myocardium, as a result of interruption of the blood supply to the area, as in coronary thrombosis. "Cardiomyocyte‐specific overexpression of ERRγ after myocardial infarction improves cardiac function by suppressing the expression of its pro‐inflammatory downstream target GBP5, thereby inhibiting inflammasome assembly, alleviating myocardial inflammation, and pyroptosis." (PMID 40636987, 2025).
nonalcoholic fatty liver disease (1 paper, 2023). "According to the existing research, GBP1 was repressed in hepatitis B virus‐infected patients, GBP2 expression levels were enhanced in patients with nonalcoholic fatty liver disease, and overexpression of GBP5 could induce liver injury and inflammation." (PMID 37551111, 2023).
Obesity (1 paper, 2021). Accumulation of substantial excess body fat. "On the other hand, monocytes from mothers with obesity (n = 3/time point) exhibited suppression of genes involved in interferon signaling (STAT1, GBP5, PSMB8) and response to reactive oxygen species (STRBP, HEBP2, TRAP1, TRPA1) (p value <0.001) with gestational age." (PMID 34195568, 2021).
oral epithelial dysplasia (1 paper, 2024). "GBP5 was absent or weakly expressed in the normal oral epithelium and oral epithelial dysplasia (OED) adjacent to OSCC." (PMID 38978333, 2024).
osteonecrosis of the femoral head (1 paper, 2025). "In osteonecrosis of the femoral head, elevated GBP5 expression in female patients may partly explain gender differences in disease prevalence and clinical presentations." (PMID 40788157, 2025). "In osteonecrosis of the femoral head, GBP5 expression correlates with disease progression, severity, and treatment outcomes, making it a promising marker for predicting disease risk and as a therapeutic target, particularly in relation to gender-specific factors." (PMID 40788157, 2025).
pneumonia (1 paper, 2022). An acute, acute and chronic, or chronic inflammation focally or diffusely affecting the lung parenchyma, caused by an infection in one or both of the lungs (by bacteria, viruses, fungi, or mycoplasma.). "Additional studies using GBP5 have also distinguished TB from non-TB pneumonia with >90% sensitivity and specificity." (PMID 35354815, 2022).
preeclampsia (1 paper, 2025). Preeclampsia is a hypertensive disorder of pregnancy that is characterized by new-onset hypertension with proteinuria presenting after 20 weeks of gestation, and depending on mild or severe forms may initially present with severe headache, visual disturbances, and hyperreflexia. "Pregnancy complications like preeclampsia are associated with altered expression of interferon-stimulated genes, including guanylate-binding protein 5 (GBP5)." (PMID 40333975, 2025).
pulmonary fibrosis (1 paper, 2025). Chronic progressive interstitial lung disorder characterized by the replacement of the lung tissue by connective tissue, leading to progressive dyspnea, respiratory failure, or right heart failure. "The Exportin 1 (XPO1) inhibitor Selinexor similarly targets GBP5 to suppress the NLRP3 pathway, alleviating pulmonary fibrosis." (PMID 40788157, 2025).